INS (insulin)
Diseases named in the same sentence as INS in open-access papers (continued):
Sharing a sentence is not in itself a finding about the gene and the disease.
diabetes (continued). "Diabetes is a chronic disorder that was the first non-communicable disease to be recognized by the United Nations as a 21st-century pandemic, and it develops either when the pancreatic β-cells do not secrete enough insulin or when the cells cannot productively use circulating insulin." (PMID 35454311, 2022). "Diabetes mellitus is a group of metabolic diseases characterized by hyperglycemia (high levels of glucose in the blood) which results from defects in insulin secretion (the pancreas does not produce enough insulin), insulin action (the body cannot effectively use the insulin it produces), or both." (PMID 35591561, 2022). "It is reported that the metabolic abnormalities in carbohydrate, fat, and protein in diabetes could be due to the lack of supply of insulin, which results from inadequate insulin secretion and/or diminished tissue responses to insulin at one or more points in the complex pathways of hormone action." (PMID 35480484, 2022). "Furthermore, insulin can be used to augment or even replace oral glycemic medications in patients with type 2 diabetes mellitus, which, if not addressed, may have resulted in those patients also being overlooked." (PMID 36011478, 2022). "However, linear growth reduction precedes CFRD and cannot be reversed with intensive insulin treatment once diabetes is diagnosed, suggesting that insulin secretory defects may play a negative role." (PMID 35358060, 2022). "Because the etiology of diabetes in the Japanese population is characterized by lower insulin secretion and insulin resistance, we thought that diminished insulin secretion might have a direct impact on developing diabetes especially in a lean or non-obese population." (PMID 35010830, 2022). "Diabetes mellitus (DM) is a chronic NCD that develops when the pancreas does not produce enough insulin or the body cannot effectively use insulin." (PMID 36510178, 2022). "Our study showed higher RRs for prevalent erectile dysfunction in men with SIDD after adjustment for the clustering variables, suggesting that low insulin levels not yet compensated with insulin therapy might be involved in erectile dysfunction in men newly diagnosed with diabetes." (PMID 34800144, 2022). "However, patients with diabetes have a particularly high insulin need, due to the decreased insulin sensitivity during acute illness (inflammation) combined with the lack of insulin in patients with type 1 diabetes mellitus (T1DM) or insulin resistance in T2DM." (PMID 36992742, 2022). "LADA is usually defined as follows: onset of diabetes over 30 years of age, presence of autoantibodies against Glutamic acid decarboxylase (GADA), and/or other beta cell associated antibodies, and no need for insulin treatment during the first 3-6 months after diabetes has been diagnosed." (PMID 35923626, 2022). "While an urban male interviewee could resort to trying to buy medications from local pharmacies, a rural female interviewee who needed insulin injections could not get her medicine in the absence of public provision, significantly limiting her capacity to care for her diabetes." (PMID 36962280, 2022). "Regarding barriers to insulin initiation, most of the PCPs admitted that their patients were resistant and unwilling to begin insulin mainly due to fear of injections, lack of education about diabetes, fear of hypoglycemia, and difficult administration technique in addition to others." (PMID 36554673, 2022). "In addition, researchers have found that there is a positive correlation between abdominal adipose tissue and the homeostasis model assessment of insulin resistance (HOMA-IR) in elderly white men without diabetes and a negative correlation with insulin sensitivity." (PMID 35237639, 2022).
diabetes (continued). "Results of this study suggest the group reporting taking insulin exhibited a pattern of higher quality regarding dietary intake for the foods they consumed frequently and that contributed most to energy compared to those with T2D not using insulin and participants without diabetes." (PMID 36014790, 2022). "Diabetes mellitus (DM) is a chronic disease that occurs when the pancreas is no longer able to make insulin or when the body cannot make good use of the insulin it produces." (PMID 35990823, 2022). "Due to the long-term basal insulin release by this combination of nanoparticle and hydrogel, which might reduce the frequency of injections of patients, this may assist not just the elderly with diabetes but also patients from other age groups." (PMID 36545679, 2022). "Furthermore, increased CD34-positive α-cells in the pancreatic islets of diabetes models indicated that some β-cell may undergo transdifferentiation rather than apoptosis in the progression of diabetes and also lose the function of INS secretion." (PMID 36467676, 2022). "Therefore, all T1D subjects in this study diagnosed at > 30 years-of-age were only included if they were not obese and all diabetics had to have started insulin therapy within 1 year of diagnosis, with all children and adolescents having had to start insulin therapy immediately at diagnosis." (PMID 35843941, 2022). "Interestingly, subjects with sustained diabetes remission compared to those with relapse had less hepatic VLDL1-triglyceride production and VLDL1-palmitic acid content, no re-accumulation of pancreatic fat and maintained the first-phase insulin response by 2 years." (PMID 35806437, 2022). "Similarly, no information on insulin sensitivity or secretion was available, which could have provided additional insights relative to metabolic pathways in pre-diabetes." (PMID 35086546, 2022). "Evidence of insulin production was demonstratable both histologically and biochemically, but insulin signaling was suppressed in the liver, and drops in blood glucose were observed following ricin injection in streptozotocin (STZ)-induced diabetes, indicating excess insulin is not the cause." (PMID 36548717, 2022). "Diabetes mellitus (DM) is a noncommunicable disease (NCDs) that includes a group of metabolic conditions characterized by hyperglycemia and resulting from defects in insulin action, insulin secretion or both." (PMID 36364077, 2022). "The traditional criteria of MODY (people with diabetes diagnosis <25 years, non‐insulin treated and an affected parent) are based on the absolute age of diagnosis cut‐offs and have shown a significant lack of sensitivity identifying less than 50% of monogenic diabetes." (PMID 35822264, 2022). "It reliably predicts fasting blood glucose level (BGL) of diabetes mellitus (DM) patients, either with or without insulin injections." (PMID 35444228, 2022). "Diabetes mellitus (DM) is a chronic metabolic disorder with the main characteristic of elevated blood glucose levels, either due to insufficient or lack of insulin secretion, resistance to its action, or both." (PMID 35499716, 2022). "Diabetes mellitus (DM) is a disease in which the body does not generate an adequate amount of insulin or develops insulin resistance, resulting in increased blood sugar levels." (PMID 36258952, 2022). "Second, our study is based on administrative hospital claims data that do neither contain information on the duration of diabetes - thus DKA events may have occurred in newly diagnosed as well as in established disease – nor do they contain medication data (e.g. insulin pump usage)." (PMID 36093075, 2022). "The other main type of DM is type 1 diabetes(T1DM), characterized by the autoimmune destruction of pancreaticβ cells, which generally culminates in the total inability tosecrete insulin." (PMID 35924548, 2022).
diabetes (continued). "Furthermore, as insulin secretion in T2D can be enhanced by drugs that bypass the metabolic steps (such as sulphonylureas or GLP-1-based therapies), it appears insulin content is also not limiting and thus that metabolic failure plays a critical role in diabetes development." (PMID 36376280, 2022). "Although the isolation of insulin in 1921 marked a panacea that has drastically transformed diabetes from a terminal to a treatable illness, the precise temporal glucose control supplied by endogenous insulin-producing β-cells is not matched by the current methods of insulin delivery." (PMID 36139388, 2022). "This may be because our participant received medical nutrition therapy after diagnosis, including interventions such as diet, exercise, and insulin therapy, these interventions result in good glycemic control so that they do not progress to severe uncontrolled diabetes." (PMID 35872998, 2022). "In this context, we hypothesized that combining basal insulin with a GLP1-RA in early T2DM may provide a strategy that could enhance the achievability of the desired metabolic outcomes of improved beta-cell function and diabetes remission, while limiting the risks of hypoglycemia and weight gain." (PMID 36244997, 2022). "Diabetes mellitus (DM) is one of the most common metabolic disorders marked by chronic hyperglycemia and occurs when the body is not able to properly manage insulin secretion, insulin function, or bot." (PMID 35711333, 2022). "Patients with a new diagnosis of diabetes mellitus (DM) or with sudden worsening of preexisting DM after starting treatment with ICIs, with a random 5 hour-postprandial C-peptide value of <0.6 nmol/L and without possibility of subsequent withdrawal of insulin treatment, were included." (PMID 36387939, 2022). "Diabetes mellitus (DM) is a serious chronic disease that occurs when there is no optimal use of insulin in the organism due to a lack of insulin production or because the organism cannot properly use the insulin that is produced due to insulin resistance." (PMID 35270046, 2022). "However, in conditions of IR and diabetes, due to the lack of regulation of insulin signaling, overactive FoxO1 continues to promote gluconeogenesis in an uncontrolled manner, leading to hyperglycemia and ultimately participating in the occurrence of diabetes and its complications and development." (PMID 36147338, 2022). "Interestingly, the change in BMI was higher in the population without developing diabetes than that with developing diabetes in the population with BMI < 22.0 kg/m2 in this study, which might mean diminished insulin secretion." (PMID 35010830, 2022). "However, it cannot be excluded that alpha-lipoic acid could be used to prevent rather than treat the alteration in insulin sensitivity that may precede the development of diabetes by years." (PMID 36615676, 2022). "As a global prevalent metabolic disease, diabetes mellitus (DM) is characterized by a lack of insulin production or cellular uptake of insulin (2018)." (PMID 36339532, 2022). "Diabetes mellitus (DM) is an endocrine disorder characterized by a relative or absolute lack of insulin due to the dysfunction or destruction of β-cells." (PMID 35979435, 2022). "Diabetes mellitus (DM) is diagnosed based on a high serum glucose level due to a lack of insulin secretion, absence of insulin receptor responsiveness, or both." (PMID 35434481, 2022). "Diabetes mellitus (DM) is a chronic systemic metabolic disease in which the pancreas is incapable of producing enough insulin, or the insulin does not work and cannot send the signal into tissues to consume blood glucose." (PMID 35056393, 2022). "Notably, diet soft drink was the 4th most frequently consumed food subcategory among the group reporting taking insulin, the 7th among those with T2D but not taking insulin, and did not appear in the top 10 food subcategory frequency list among those without diabetes." (PMID 36014790, 2022).
diabetes (continued). "In a retrospective study of 562 individuals with and without diabetes, critically ill patients affected by COVID-19 spent significantly less time in the normal range of glucose levels (70–150 mg/dL) than non-COVID-19 individuals (44.4% vs. 68.5%), with a higher need of daily insulin dose." (PMID 34482534, 2022). "In particular, the lack of plasma insulin limited the ability to explore the concordance between METS-IR and HOMA-IR, and patients with diabetes could not be classified in the study because insulin testing is not a routine physical examination, especially in large epidemiological studies." (PMID 36992743, 2022). "MODY patients typically exhibit hyperglycaemia but are not insulin resistant, and thus the GENA348 mouse represents a novel model to investigate early changes to mitochondrial function and importantly, new insights into the early progression of other more pathogenic forms of diabetes." (PMID 35046471, 2022). "The “hyperglucagonemia” of diabetes appears to be nonexistent in either obesity with insulin resistance or T2D (hereafter referred to collectively as T2D), but it may be present at moderate levels in insulin‐dependent T1D." (PMID 35569125, 2022). "Diabetes mellitus (DM) is a group of metabolic disorders characterized by increased blood glucose levels due to the absence of insulin secretion or defects in insulin action." (PMID 35003299, 2021). "However, at P70 we observed high insulin levels in control HFO mice suggesting that their beta-cells were able to mount a compensatory response which may have prevented them from progressing to beta-cell failure and diabetes." (PMID 34234216, 2021). "Diabetes mellitus (DM) is a condition in which blood hyperglycemia occurs and cannot be controlled due to a lack of insulin activity." (PMID 33435419, 2021). "Finally, although participants using insulin were not excluded, the results may not be generalizable to patients exclusively using injectables to manage their diabetes." (PMID 34114964, 2021). "We previously found that any increases in diabetes risk in HIV-infected participants in the CICADA cohort were associated with inflammation-related insulin resistance in ART-naive patients, so it appears that this, rather than decreased insulin production, is key." (PMID 33740034, 2021). "Diabetes mellitus (DM) is a common metabolic disorder and is described by decreased insulin secretion by pancreatic β-cells or lack of responses of the body to insulin." (PMID 34500753, 2021). "Moreover, the lack of significant differences in insulin levels in the brains of non-diabetic group with diabetes could possibly dictated by insulin-degrading enzyme (IDE) activity in diabetes mouse." (PMID 33918576, 2021). "Diabetes mellitus (DM) is a chronic disease that occurs when the pancreas does not produce enough insulin or the body cannot use the insulin produced effectively." (PMID 34055007, 2021). "Diabetes mellitus (DM) is a chronic disease in which blood sugar levels increase due to relative or absolute lack of insulin." (PMID 34946716, 2021). "Glucocorticoid (GC)-exacerbated hyperglycemia is prevalent in hospitalized patients with diabetes mellitus (DM) but evidence-based insulin guidelines in inpatient settings are lacking." (PMID 34529703, 2021). "Thus, pharmacological intervention that can target the mTOR pathway to deactivate the negative feedback loop to reverse insulin resistance, maintain nutrient homeostasis, regulate cellular growth and proliferation will be useful in the prevention and/or treatment of diabetes." (PMID 34445300, 2021). "Aside from taking insulin/medication or being on a special diet, we also could not examine whether individuals engaging in behavioural factors did so specifically in order to help manage their diabetes." (PMID 34789208, 2021).
diabetes (continued). "In this work, we find that blockade of KCNH6 channels by BBR increases insulin secretion in a high-glucose-dependent manner or only under hyperglycemic conditions, suggesting that BBR is a glucose-dependent insulin secretagogue for the treatment of diabetes that does not cause hypoglycemia." (PMID 34556670, 2021). "Diabetes mellitus (DM) is considered chronic disease in which the required amount of insulin is not produced by the body or insulin is not properly used by the body, resulting in excessively high blood sugar (glucose) levels." (PMID 34884099, 2021). "Although insulin could protect cardiomyocytes this effect is weakened or absent in diabetes." (PMID 33613101, 2021). "Diabetes mellitus (DM) describes a group of metabolic disorders of the carbohydrate metabolism that are based on (absolute or relative) lack of insulin and that lead to chronic hyperglycemia." (PMID 35720761, 2021). "Diabetes mellitus (DM) is a public health issue in which the patient either does not produce enough insulin or does not respond appropriately to insulin, and it is estimated to affect over 400 million people worldwide." (PMID 34730682, 2021). "Moreover, although DLS may regulate somatostatin/insulin release by transplanted islets, it did not improve blood glucose levels, body weight, and glucose tolerance in a mouse model of diabetes that received islet transplantation." (PMID 34711885, 2021). "In addition, a previous study demonstrated that hypoxia increased blood [glucose], possibly through decreasing insulin production or sensitivity, which may also exacerbate the negative effects of uncontrolled diabetes (i.e., hyperglycemia)." (PMID 34337893, 2021). "In addition to poorly controlled type 2 diabetes mellitus requiring insulin treatment, high non-HDL-C levels may be another contributing factor to the development of scleroedema." (PMID 33952255, 2021). "Notably, both WT and eLrrc8a KO mice were found to be equally glucose-intolerant and insulin-resistant, indicating that these differences in microvascular dysfunction were not due to increased hyperglycemia and more severe diabetes in eLrrc8a KO mice." (PMID 33629656, 2021). "Thus, older rather than younger males with CAS may be less sensitive to insulin, leading to a shorter length of time in developing diabetes." (PMID 34104095, 2021). "HOMA-β has been shown to be moderately correlated with insulin secretion measured using hyperglycemic clamps, continuous infusion of glucose with model assessments, and acute insulin response estimated using the intravenous glucose tolerance test in both individuals with and without diabetes." (PMID 34442147, 2021). "Among diseased patients with diabetes the algorithm was not used for the following reasons: 3 patients died in the first days of hospitalization, 5 had capillary blood glucose values lower than the target without insulin, and 1 patient was managed during hospitalization with intravenous insulin." (PMID 33916210, 2021). "Diabetes mellitus (DM) is chronic disease happened due to rising blood sugar level because of the body cannot produce at all or secrets insufficient insulin hormone or not use it effectively." (PMID 33494764, 2021). "In addition, there were lower rates of CVDs and diabetes medicines and very low to no dispensing of insulin in some governorates that were partly controlled by the Syrian government compared to other governorates that were completely or mostly controlled by the Syrian government." (PMID 34645430, 2021). "Diabetes mellitus (DM) is a metabolic disease, now prevalent worldwide, which is characterized by a relative or absolute lack of insulin secretion leading to chronically increased blood glucose levels." (PMID 33995278, 2021).